GSK3B (glycogen synthase kinase 3 beta)
Diseases named in the same sentence as GSK3B in open-access papers (continued):
Sharing a sentence is not in itself a finding about the gene and the disease.
Parkinson disease (81 papers, 2008 to 2026). A progressive degenerative disorder of the central nervous system characterized by loss of dopamine producing neurons in the substantia nigra and the presence of Lewy bodies in the substantia nigra and locus coeruleus. "Dysregulation of GSK3β activity has been implicated in neurodevelopmental disorders and neurodegenerative diseases, such as Alzheimer’s disease and Parkinson’s disease." (PMID 38139062, 2023). "Particularly, GSK3β is widely present in the brain and is associated with several neurodegenerative diseases, including Parkinson’s disease (PD), AD and Huntington’s disease (HD)." (PMID 32326204, 2020). "Therefore, we investigated the neuroprotective role of Netrin‐1 in dopaminergic neurons, focusing on its regulation of DRD2/GSK3β signaling and its potential to suppress ROS generation key pathways implicated in Parkinson's disease progression." (PMID 41249856, 2025). "GSK3β activity is also reported to be associated with LRRK2-G2019S parkinsonism and sporadic PD." (PMID 33231564, 2020). "In Parkinson's disease models, GSK3β activation has been shown to facilitate α‐synuclein aggregation and dopaminergic neuronal loss through mechanisms involving mitochondrial dysfunction, oxidative stress, and proinflammatory signaling pathways such as NF‐κB." (PMID 41249856, 2025). "Background/Objectives: Glycogen synthase kinase-3 beta (GSK3β) is a key enzyme involved in neurodegenerative diseases such as Alzheimer’s and Parkinson’s, contributing to tau hyperphosphorylation, amyloid-beta (Aβ) aggregation, and neuronal dysfunction." (PMID 40573222, 2025). "In this study, we demonstrate that Netrin‐1 plays a crucial neuroprotective role in Parkinson's disease (PD) by regulating dopaminergic neuronal survival through modulation of DRD2/GSK3β signaling and suppression of oxidative and inflammatory stress." (PMID 41249856, 2025). "The GSK3B and BCL-2 also scored high in MCC, reinforcing their importance in the core network modules associated with parkinsonism." (PMID 40404673, 2025). "The abnormal activity of GSK3β appears to be important in the development of neurodegenerative diseases such as Alzheimer’s and Parkinson’s disease, making this enzyme an attractive biological target for drug discovery." (PMID 38139062, 2023). "For example, a LC3-II increase and a LAMP2A decrease have been reported in the substantia nigra of Parkinson’s disease models, as well as an alteration of GSK-3β and TDP-43 in some forms of dementia, and an impairment of LC3-II and p62 in epilepsy." (PMID 36613513, 2022). "Disruption of the VAPB‐PTPIP51 tethers by Parkinson's disease‐linked α‐synuclein involves its direct binding to VAPB, and GSK3β is a known negative regulator of the VAPB‐PTPIP51 interaction." (PMID 35026048, 2022). "Inhibitors of GSK3β provide therapeutic benefit in models of AD, Parkinson’s disease (PD), and spinal cord lesion." (PMID 36293516, 2022). "It has been reported that one of the pathogenesis of Alzheimer and Parkinson are the inactivation of Wnt signaling by regulating the activation of GSK3β or high leveled DKK131–34." (PMID 33431799, 2021). "Zhou et al16 revealed that epigallocatechin‐3‐gallate reduced apoptosis in substantia nigra neurons in Parkinson's model rats through mTOR/AKT/GSK‐3β activation." (PMID 32108985, 2020). "Activation of the TLR4/PI3K/AKT/GSK3β signaling pathway in macrophages/microglia aggravated neuroinflammation in Parkinson’s disease." (PMID 32826878, 2020). "Current studies have demonstrated oligo-porphyran offers a neuroprotective treatment for Parkinson’s disease via PI3K/Akt/GSK-3β pathway, with changes in the Bax/Bcl-2 ratio." (PMID 31168297, 2019). "In Parkinson's disease (PD), the GSK3-β inhibitor lithium decreases the aggregation and phosphorylation of α-synuclein and leads to increased autophagy." (PMID 29379583, 2017).
Parkinson disease (continued). "The brown module has 53 hub genes, including genes associated with dopaminergic signaling (GNB1, GSK3B), long-term potentiation (PPP1CB), opioid signaling (PPP2CA, PPP3CA, PPP3R1), epilepsy (SYN1), and Parkinson’s disease (SNCA)." (PMID 28710498, 2017). "Chronic treatment with lithium by virtue of its GSK3β inhibitory effect also ameliorated the disease processes in preclinical models of multiple sclerosis, Alzheimer, and Parkinson’s disease." (PMID 26979166, 2016). "The serine/threonine kinase GSK3β plays important roles in the pathogenesis of a wide variety of diseases that include neurodegenerative diseases (e.g. Parkinson's Disease), inflammatory diseases and cancer." (PMID 27602497, 2016). "GSK-3β dysregulation results in Parkinson's-like pathophysiology; meanwhile, activation of GSK-3β has been shown to facilitate numerous apoptotic conditions in PD." (PMID 27738547, 2016). "α-synuclein [α-Syn]-mediated activation of GSK-3β leading to increases in hyperphosphorylated Tau has been shown by us to occur in striata of Parkinson's diseased [PD] patients and in animal models of PD." (PMID 21812967, 2011). "The interplay with AMPK signaling further refines this regulation: activation of AMPK can inhibit GSK-3β, thereby enhancing autophagy and supporting neuronal health, particularly in Parkinson’s disease models where AMPK-mediated suppression of GSK-3β reduces neuroinflammation." (PMID 41190025, 2025). "The catalytic triad is essential for the kinase activity of GSK-3β, enabling it to regulate a wide range of signaling pathways, including those involved in cell survival, metabolism, and neurodegenerative diseases like Parkinson’s." (PMID 40404673, 2025). "Fourthly, MPP+/ MPTP treatment activates GSK3β and mediates tau phosphorylation, which is dependent on α-synuclein in Parkinsonism models such as SH-SY5Y co-transfected cells, mesencephalic neurons, transgenic mice overexpressing α-synuclein, and post-mortem striatum of PD patients." (PMID 37691228, 2024). "GSK3β is an attractive target for drug discovery since its aberrant activity is involved in the development of neurodegenerative diseases such as Alzheimer’s and Parkinson’s disease." (PMID 38139062, 2023). "This neuroprotective mechanism of ST extract against MPTP-induced Parkinsonism might be related to decreasing the phosphorylation of GSK-3β and restoring the activities of striatal antioxidant defenses to restore the nigrostriatal dopaminergic function and decrease α-synuclein accumulation." (PMID 30678114, 2019). "The neuroprotective mechanism of ST extract against MPTP-induced Parkinsonism might be related to decreasing GSK-3β phosphorylation and restoring the activities of striatal antioxidant defenses to restore the nigrostriatal dopaminergic function and decrease α-synuclein accumulation." (PMID 30678114, 2019). "Both GSK-3β and mTOR regulate numerous IGF-IRβ-dependent processes that become impaired in the course of Parkinson’s disease—including apoptosis, autophagy, neuronal metabolism, protein synthesis, and synaptic plasticity." (PMID 41154720, 2025). "This is consistent with neuroprotection research: in Parkinson’s models, PCA mediates p-GSK3β phosphorylation through PLK2, blocking its degradation of Nrf2." (PMID 41306290, 2025). "GSK-3β is known to be involved in neuronal development and suppression of GSK-3β showed the ability to reduce α-synuclein in cellular models of Parkinson’s disease." (PMID 35163631, 2022). "In a rat model of Parkinson disease, EGCG promoted the phosphorylation of AKT and GSK3β and reduced neuron apoptosis in the substantia nigra." (PMID 36776771, 2022). "The increased GSK-3β phosphorylation and activated PI3K/AKT/GSK-3β pathway induced the damage of PC12 cells and the occurrence of Parkinson's disease." (PMID 34485505, 2021).
Parkinson disease (continued). "Similarly, in a murine model of Parkinson’s disease, EGCG was found to reduce the expression of mTOR, Akt, and glycogen synthase kinase-3 beta (GSK-3β) and inhibit neuronal apoptosis." (PMID 40650253, 2025). "In Parkinson’s models, MANF manages cellular stress via endoplasmic reticulum regulation and activates antioxidant pathways through PI3K/Akt/GSK3β and AMPK/mTOR pathway to enhances mitochondrial function." (PMID 37751132, 2023). "Studies have shown that its extracts could attenuate neurological damage and improve motor dysfunction in a Parkinson’s disease model by inhibiting endoplasmic reticulum stress and activating the protein kinase B (AKT)/glycogen synthase kinase 3 beta (GSK3β)/β-catenin signaling pathway." (PMID 40564909, 2025). "Interestingly, it has been demonstrated that miR‐135a exerts a protective role via promotion of proliferation and suppression of apoptosis and neuroinflammation by targeting GSK3β in MPP+‐intoxicated SH‐SY5Y cells, providing a potential therapeutic target for the treatment of Parkinson disease." (PMID 37718696, 2024).
type 2 diabetes (79 papers, 2011 to 2026). "Elevated levels of GSK-3β have been linked to diseases like type II diabetes and neurodegenerative diseases." (PMID 39684384, 2024). "In type 2 diabetes (T2D), the insulin-mediated decrease in GS activity and glycogen synthesis is closely associated with an increase in GSK3β levels in the muscle." (PMID 36290175, 2022). "It would be of particular interest to include the insulin signalling pathway in order to explore the connection between AD and type 2 diabetes since GSK3β has been implicated in both diseases." (PMID 22482080, 2012). "Interestingly, patient studies have shown that GSK3B activity in addition with the APOE-ε4 genotype have been associated with cognitive decline in patients with type 2 diabetes." (PMID 37163077, 2024). "Type 2 diabetes (T2D) is associated with hyperactivation of GSK3β, suppressing both glycogen synthase and insulin receptor substrate 1 (IRS-1)." (PMID 37895969, 2023). "Over the past decades, dysregulation of GSK-3β has been linked to the pathogenesis of many disorders, including type 2 diabetes mellitus (T2DM), atherosclerosis, neurodegenerative diseases, and a variety of malignant tumours." (PMID 38107562, 2023). "Inhibition of GSK-3β was found to be therapeutic for type 2 diabetic glomerular injury as it allows NRF2 expression and subsequent suppression of oxidative stress, thus resulting in an improvement in podocyte injury and senescence." (PMID 41277868, 2026). "GSK3β-targeted therapeutics have protective effects on urinary albumin excretion in models of both type 1 and type 2 diabetes." (PMID 39880090, 2025). "Exposure to roxadustat reduced insulin-stimulated phosphorylation of Akt-Ser473 in myotubes from donors with type 2 diabetes and insulin-stimulated phosphorylation of GSK3β-Ser9 in myotubes from both groups." (PMID 38814443, 2024). "As demonstrated in an earlier type 2 diabetic wound model (Bitar & Al‐Mulla, 2011), the current results indicated that HFD/STZ‐induced type 2 diabetes leads to irregular Nrf2/Keap1 and Nrf2/HO‐1 signaling by unbalancing GSK‐3β/Fyn/Nrf2 signaling in the liver." (PMID 37823118, 2023). "The activation and the nuclear accumulation of Fyn are partially stimulated by glycogen synthase kinase‐3β (GSK‐3β), which reduces insulin sensitivity and hepatic glycogen storage in type 2 diabetes." (PMID 37823118, 2023). "The second insulin receptor signaling pathway, the Akt pathway—which is responsible for cell growth and survival, protein synthesis, and inhibition of the glycogen synthase kinase-3β (GSK-3β) enzyme —is also affected by both AD and type 2 diabetes." (PMID 36232867, 2022). "Activated GSK3β was elevated in DN mice and type 2 diabetic patients, which is correlated the severity of DN and ECM accumulation." (PMID 36225562, 2022). "In this way, type 2 diabetes and cardiovascular complications are closely related to an impaired serine/threonine kinase (Akt)/glycogen synthase kinase 3 beta (GSK-3β) pathway." (PMID 34589130, 2021). "Inhibition of GSK3β improves glucose tolerance in type 2 diabetic mice, while increased activation of GSK3β contributes to type 2 diabetes." (PMID 32992509, 2020). "GSK3β has also been shown to be related to imbalanced mitochondrial dynamics in the hippocampus of mice with type 2 diabetes and a human neuronal cell line via a Drp1-dependent mechanism." (PMID 32903692, 2020). "Western blot findings demonstrated that polysaccharides enhanced the protein expressions of IRS2, PI3K, and glycogen synthase and lowered that of GSK-3β in the liver of type 2 diabetic mice." (PMID 31337059, 2019). "Collectively, we have shown that the conditions which mimic those of type 2 diabetes increased GSK3β activity in HAECs." (PMID 27534430, 2016).
type 2 diabetes (continued). "Establishing the role of this site in vivo as well as potential functional interplay with previously identified GSK-3 sites has important implications for exploring GSK-3β as a therapeutic target to treat hyperlipidaemia of type-2 diabetes and obesity." (PMID 26589965, 2015). "TUDCA normalized levels of GRP78 and GRP94 and mitochondrial GSK-3β in the rat model of type 2 diabetes." (PMID 22144992, 2012). "The data support the importance of controlling both hyperglycemia and hyperlipidemia in the management of Type 2 diabetes, and identify pancreatic islet β-cell Gsk3β as a potential therapeutic target." (PMID 21541314, 2011). "Therefore, this study aims to systematically investigate how sinapine modulates hepatic glycogen synthesis and lipid metabolism in type 2 diabetes via the IRS1–PI3K–Akt–GSK3β–GS signaling pathway." (PMID 41497732, 2026). "Since the mid-1990s, GSK3β has been considered as a therapeutic target for type 2 diabetes." (PMID 37895969, 2023). "In conclusion, MG extract may exert antidiabetic effects by augmenting the antioxidant defense system through the regulation of GSK‐3β/Fyn/Nrf2 in a rat model of type 2 diabetes." (PMID 37823118, 2023). "However, in type 2 diabetes, elevated activity of GSK-3β is proposed to trigger the reduction in glucose clearance by developing insulin resistance." (PMID 36232867, 2022). "This hypothesis is further supported by numerous studies showing increased GSK-3β activity in type 2 diabetes patients." (PMID 32365965, 2020). "Therefore, isopyrrolonaphthoquinones and similar structures can be considered as possible candidates for the development of drugs in order to treat diseases related to the biological target GSK-3β, such as diabetes type 2, neurological disorders, or cancer." (PMID 27827848, 2016). "In type 2 diabetes increased GSK-3β activity might lead to an elevation of Aβ production and increased tau phosphorylation." (PMID 26136647, 2015). "However, this study was in contrast to another study that showed that TUDCA normalized levels of GRP78 and GRP94 and mitochondrial GSK-3β in the rat model of type 2 diabetes resulted in significant prevention of diabetic cardiac damage." (PMID 22144992, 2012). "Our study revealed a significant relative increase in liver GSK‐3β (p < .0001), Fyn (p < .01), and Keap‐1 (p < .0001) levels by 53%, 53%, and 38%, respectively, in response to the induction of type 2 diabetes compared to the levels observed in healthy control rats." (PMID 37823118, 2023). "TDZD-8-mediated GSK-3β inhibition has been investigated in other pathological contexts, including type II diabetes mellitus and various inflammatory diseases, suggesting that GSK-3β inhibition via TDZD-8 could be an effective therapeutic strategy for a broad range of pathologies." (PMID 37108703, 2023). "Therefore, GSK3β has been suggested as a therapeutic target for type 2 diabetes." (PMID 32992509, 2020). "Insulin stimulation led to increased phosphorylation of Akt-Ser473, AS160-Thr642 and GSK3β-Ser9 in myotubes from both donors with NGT and type 2 diabetes." (PMID 38814443, 2024). "Exposure to roxadustat led to a reduction in insulin-stimulated phosphorylation of Akt-Ser473 and GSK3β-Ser9, and an increase in insulin-stimulated phosphorylation of AS160-Thr642 in myotubes from donors with type 2 diabetes." (PMID 38814443, 2024). "Thus, pharmacological inhibition of GSK3β could be substantial in type 2 diabetes treatment." (PMID 33150068, 2020). "Moreover, network pharmacology study involve common targets of bergaptol and type 2 diabetes, which was further applied for gene ontology suggested INSR, NF-κB, Akt and GSK-3β targets for the insulin signalling and resistance both." (PMID 40126146, 2025). "Circadian rhythmicity determined by JTK_CYCLE was found in gene expression of glycogen synthase 1 (GYS1) for type 2 diabetes patients only, but not for its inhibitory regulator – the glycogen synthase kinase 3 beta (GSK3b)." (PMID 27756900, 2016).
type 2 diabetes (continued). "In addition to GSK3β, changes in AMPK activity in our HAEC model of type 2 diabetes could contribute to alterations in lysosome acidification." (PMID 27534430, 2016).